S100A4 (S100 calcium binding protein A4)
Diseases named in the same sentence as S100A4 in open-access papers (continued):
Sharing a sentence is not in itself a finding about the gene and the disease.
tumor (continued). "The immunohistohemical staining pattern and distribution of OPN, S100A4 and ephrin-A1 in the tumor tissues have been described previously." (PMID 24215488, 2013). "S100A4, also called metastasin, has been shown to promote tumor growth and metastasis in several tumor models." (PMID 23667563, 2013). "In the present study, quantitative RT-PCR revealed the presence of S100A4 mRNA in non-tumor mucosal samples from young patients." (PMID 23760193, 2013). "When the data was pooled, there were significant associations between high S100A4 expression and tumour location, lymph node metastasis, nodal status, TNM stage, and tumour depth." (PMID 24188373, 2013). "The importance of S100A4, a Ca2+-binding protein, in mediating tumour cell migration, both intracellularly and extracellularly, is well documented." (PMID 23469180, 2013). "This systematic review and meta-analysis demonstrates that high S100A4 expression seemed to correlate with tumour progression and prognosis of CRC patients treated by surgery or chemotherapy in different study regions." (PMID 24188373, 2013). "S100A4 is directly involved in the formation of metastasis from several different tumor types via increased cell motility and invasion." (PMID 23783026, 2013). "This meta-analysis indicates that S100A4 overexpression seems to correlate with tumour progression and poor prognosis of CRC patients." (PMID 24188373, 2013). "Transcript levels of β-catenin and S100A4 were correlated with IHC findings at the tumor invasive margin; β-catenin (r = 0.369, p = 0.003) and S100A4 (r = 0.504, p < 0.0001)." (PMID 23783026, 2013). "Obviously, the molecular mechanisms of S100A4 promotion of tumour progression need a more comprehensive understanding." (PMID 24188373, 2013). "Other salicylic amides have previously been described as inhibitors of tumor growth, including niclosamide that has shown anti-tumor activity in models that are dependent on S100A4." (PMID 23667563, 2013). "A more extensive knowledge of the proteins interacting with S100A4 and the signaling pathways involved in tumor and EC, will undoubtedly be a further step in understanding the process of angiogenesis and metastasis." (PMID 24023743, 2013). "S100A4 is a member of the S100 family of calcium-binding proteins known to be involved in tumor metastasis." (PMID 23476112, 2013). "S100A4 is a protein closely related to cellular differentiation and tumor occurrence, metastasis, and prognosis." (PMID 23693134, 2013). "The mechanisms by which the decreased expression of MMP9 and MMP10 and the increased of TIMP4 are responsible for the depressed growth and invasion of tumor cells due to S100A4 silencing, are currently being investigated in our laboratory." (PMID 22200787, 2012). "In general, S100A4 is not expressed in normal lung epithelium, whereas a variety of cells in the tumor microenvironment are S100A4-positive, including lymphocytes, fibroblasts and smooth muscle cells." (PMID 22853000, 2012). "For tumors with strong cytoplasmic S100A4 immunoreactivity, the mean tumor diameter was 2.6 cm, whereas the mean diameter for S100A4c-negative or weakly stained tumors was 3.4 cm (p = 0.02, independent samples t-test)." (PMID 22853000, 2012). "S100A4 expression is associated with epithelial mesenchymal transition (EMT), a tumor-cell invasion process that results in the loss of epithelial characteristics and the acquisition of mesenchymal features." (PMID 23166536, 2012). "Several studies have reported strategies to decrease S100A4 expression in cell lines and tumor tissue." (PMID 22878175, 2012). "The reduction of S100A4 expression in tumor tissue of transplanted HCT116-LUC-shS100A4 mice was verified by qRT-PCR." (PMID 22878175, 2012). "The staining intensity of S100A4 and ephrin-A1 was generally homogenous across the sections, indicating that the obtained results are indeed representative of the whole tumor section." (PMID 22853000, 2012).
tumor (continued). "When we analyzed changes in the expression of genes associated with S100A4-mediated metastasis formation, we observed a significant decrease of matrix metalloproteinase (MMP) 9 in the tumor tissue derived from HCT116-LUC-shS100A4 cells." (PMID 22878175, 2012). "In vivo, depletion of PMN-MDSC reduced the density of vimentin and S100A4 expressing cells in the primary tumor." (PMID 21980263, 2011). "In summary, we have demonstrated that RANTES and S100A4 reciprocally stimulating each other participate in a pathway conferring more pronounced metastatic phenotype on tumor cells." (PMID 20442771, 2010). "Altogether, the data presented strongly validate the pro-metastatic function of S100A4 in the tumor microenvironment and define how the tumor cell-derived cytokine RANTES acts as a critical regulator of S100A4-dependent tumor cell dissemination." (PMID 20442771, 2010). "We also demonstrated feedback effects of extracellular S100A4 on tumor and stroma cells, including activation of cytokines and RANTES in particular." (PMID 20442771, 2010). "Given the critical extracellular role of S100A4 during tumor progression, we explored the mechanisms responsible for the active release of S100A4 in the tumor microenvironment." (PMID 20442771, 2010). "Altogether, the data verified the significance of RANTES/S100A4 alliance in the stimulation of the malignant properties of tumor cells and pointed its possible role in development of organospecific metastases." (PMID 20442771, 2010). "For these experiments we used CSML100 tumor cells which have been shown to form large amounts of S100A4-carrying microvesicles upon stimulition." (PMID 20442771, 2010). "Strong upregulation and release of the metastasis-inducing S100A4 protein was demonstrated in tumor stroma." (PMID 20442771, 2010). "Immunostaining of tumour sections with anti-S100A4 polyclonal antibodies that recognise both human and murine S100A4 revealed the presence of numerous S100A4-positive cells in the stroma." (PMID 20723242, 2010). "The S100A4 protein is produced by murine fibroblasts and macrophages which were found in larger numbers in tumour xenografts from co-injections." (PMID 20723242, 2010). "We found that RANTES stimulates the externalization of S100A4 via microparticle shedding from the plasma membrane of tumor and stroma cells." (PMID 20442771, 2010). "The average murine S100A4 concentration in TIFs from MCF7S1 + HMF3s tumours was 2.5-3-fold higher than in TIFs from MCF7S1 tumours." (PMID 20723242, 2010). "We studied the interplay between the tumor cell-derived cytokine regulated-upon-activation, normal T-cell expressed and secreted (RANTES; CCL5) and S100A4 which were shown to be critical factors in tumor progression." (PMID 20442771, 2010). "Altogether, these observations indicate an important extracellular role of S100A4 in vivo and suggest a putative active role of S100A4 in the tumor milieu, most likely in its proinflammatory pathway(s)." (PMID 20442771, 2010). "Secretion of S100A4 from tumor and stroma cells was demonstrated in vitro and elevated S100A4 protein levels were detected in blood of S100A4 transgenic mice." (PMID 20442771, 2010). "Animal studies performed indicate that overexpression of RANTES in tumor cells confers more pronounced metastatic phenotype on tumor cells independently on S100A4." (PMID 20442771, 2010). "We previously suggested the existence of soluble tumor cell-derived factor(s) which induces the stimulation of S100A4 externalization from different tumor stroma cells." (PMID 20442771, 2010). "To investigate the significance of the RANTES/S100A4 pathway in tumor development and metastases, we generated RANTES-expressing VMR and CSML0 cell lines and the corresponding mock-infected counterparts." (PMID 20442771, 2010). "Xenograft tumour tissues were assessed by histology and immunohistochemistry and frozen tissues were used for the detection of S100A4 and RLN2." (PMID 18718015, 2008).
tumor (continued). "When injected subcutaneously in nude mice, all xenograft tumours derived from MDA/RLN2 transfectants contained reduced or almost undetectable levels of S100A4 protein when compared with the MDA/EGFP tumour tissues." (PMID 18718015, 2008). "This was comparable with another study which showed that S100A4 over expression directly correlated with tumor progression." (PMID 18771601, 2008). "S100A6 significantly correlated with tumours arising in the supratentorial region of the brain (P<0.001) and S100A4 correlated with age at diagnosis under 3 years (P=0.038)." (PMID 18781180, 2008). "S100A6 significantly correlated with supratentorial tumours (P<0.001) and S100A4 with patients under the age of 3 years at diagnosis (P=0.038)." (PMID 18781180, 2008). "Among them, five proteins, including cyclophilin-A, S100A4, profilin-1, thymosin beta 4 and 10, which previously correlated to tumor progression, were identified at the progressive stage." (PMID 18796163, 2008). "The aim of this study was to investigate short-term and long-term effects of relaxin on cancer cell motility and S100A4 expression and to determine the long-term effects of relaxin on in vivo tumour growth in an oestrogen-independent context." (PMID 18718015, 2008). "S100A4, also named metastasin, is a known promoter of tumour invasiveness and growth, and was demonstrated to increase invasiveness in mouse mammary carcinoma cells and in a transgenic mouse model." (PMID 18718015, 2008). "Stable MDA/RLN2 transfectants produced smaller xenograft tumours containing reduced S100A4 protein levels in vivo." (PMID 18718015, 2008). "S100A4 is located both in the cytoplasm, extracellularly, and also in the nucleus of tumor cells, but the mechanisms for transport and homing to subcellular compartments remains largely unexplored." (PMID 18554396, 2008). "It was reported that over expression of S100A4 protein is closely correlated with many functions for tumor aggressiveness, such as lymph node metastasis." (PMID 18771601, 2008). "We propose a novel causal relationship between relaxin expression, attenuated expression of S100A4 and reduced tumour growth." (PMID 18718015, 2008). "In contrast, pro-metastatic S100A4 displayed evidence of hypomethylation relative to the normal cerebellum in a significant proportion primary tumours (7 out of 41, 17%) and cell lines (3 out of 9, 33%), which was associated with its elevated expression." (PMID 17579622, 2007). "Recent studies of an S100A4-deficient mouse model provided in vivo evidence that expression and release of S100A4 from activated stroma cells in tumour are central both for stimulation of tumour development and metastasis formation." (PMID 15900299, 2005). "The S100A4 expression was much higher at the tumour-invading front and in the metastatic tumours as compared to the primary tumours." (PMID 16265347, 2005). "S100A4 is known to be involved in the tumour invasion and metastasis by virtue of its ability to activate nonmuscle myosin." (PMID 16265347, 2005). "Studies to determine the mechanistic basis for S100A4 function have shown a potential role for S100A4 in several different facets of tumour progression including motility, invasion, and apoptosis." (PMID 15900299, 2005). "Proangiogenic capacity of S100A4 in vivo and its influence on endothelial cells' motility in vitro was the first indication of the extracellular significance of S100A4 in tumour progression." (PMID 15900299, 2005). "Significantly higher S100A4 expression was seen in metastatic tumours as compared to primary tumours (P<0.01) even though S100A4 overexpression was present in primary tumours when compared with normal thyroid tissue (P<0.01)." (PMID 16265347, 2005).
tumor (continued). "Inhibition of S100A4 in tumour cells results in the downregulation of their invasive properties and reduces the expression of MMPs and TIMPs." (PMID 15900299, 2005). "It was found that the progeny from mice overexpressing S100A4 crossed with mice overexpressing the HER2/Neu oncogene develop tumours that metastasize more frequently and more rapidly than tumours in the parental neu mice." (PMID 15900299, 2005). "The S100A4 has recently emerged as an important protein with the capacity to promote invasion and metastasis of many human neoplasms." (PMID 16265347, 2005). "S100A4 staining was mainly cytoplasmic, heterogeneous in some tumours with tendency to more intense staining in invading fronts than in central portions of the tumour samples." (PMID 16265347, 2005). "Two permanently growing cell clones were established from the mammary gland tumours of a bitransgenic neu/S100A4 mouse and termed PN1 and PN2." (PMID 14710237, 2004). "Tumours produced by the PN2 cell line showed higher levels of staining for S100A4 than the tumours produced by the other two cell lines, particularly for the spindle cell component." (PMID 14710237, 2004). "The frequency of tumour metastasis, however, remained the same in the neu/S100A4 tumour-derived PN2 cell line as in the neu/S100A4 transgenic mice, with only 50% of mice with mammary gland tumours developing lung metastases." (PMID 14710237, 2004). "Additional cell lines expressing both Neu and S100A4 have also been derived by transfection of rat S100A4 cDNA into tumour cell lines cloned from neu single transgenic mice." (PMID 14710237, 2004). "The tumours produced by the 8Neup9Ka cell line showed a low to moderate staining for S100A4, which varied within each tumour." (PMID 14710237, 2004). "In normal breast tissue adjacent to the tumour S100A4 protein expression was detected in a variety of different cell types." (PMID 12439718, 2002). "S100A4 is a known protein that promotes tumor invasion and metastasis by regulating the interaction between the cytoskeleton and extracellular matrix, enhancing the migration ability of tumor cells." (PMID 39852172, 2025). "The results of in vivo experiments similarly indicated that downregulation of S100A4 expression could increase the sensitivity of tumor cells to cytarabine and inhibit tumor growth." (PMID 40584630, 2025). "Consistently, S100a4 -/- mice are protected from both primary tumor growth and metastasis." (PMID 40078995, 2025). "Thus, it is important to understand the overarching immunomodulatory impact of S100A4 within the tumor microenvironment (TME), which has important implications for immunomodulatory therapies." (PMID 40078995, 2025). "Additionally, S100A4, a known tumor metastasis-promoting factor, is highly expressed in various tumors and is associated with enhanced tumor aggressiveness and metastatic capability." (PMID 39852172, 2025). "Our study further found that S100A4 is expressed in macrophages, suggesting that macrophage-derived S100A4 may also play a role in suppressing the tumor immune microenvironment." (PMID 40772225, 2025). "In vivo, TFP suppresses tumor growth in GBM xenograft models, though it is unclear whether this is associated with its modulation of S100A4 function." (PMID 40078995, 2025). "Multiple studies have shown the overexpression of S100A4 in tumor cells." (PMID 40093000, 2025). "S100A4 is primarily highly expressed in stromal cells of the tumor microenvironment, where it works by promoting angiogenesis and recruiting immune cells to modify the tumor microenvironment and induce the release of some of the cytokines and growth factors that promote cancer development." (PMID 41173847, 2025). "Additionally, S100A11 and S100A4, as calcium-binding proteins, have been reported to promote tumor metastasis by activating inflammatory pathways such as NF-κB." (PMID 40740857, 2025).
tumor (continued). "Bevacizumab treatment enhances tumor infiltration by neutrophils and increases S‐protein expression in neutrophils, contributing to neutrophil infiltration into tumors and increasing S100A4 expression in glioma cells, interfering with the efficacy of bevacizumab to promote tumor progression." (PMID 40979214, 2025). "Herein, we characterized the functional role of S100A4 in this tumor type." (PMID 39857966, 2025). "Here, we hypothesized that S100A4 might have prognostic significance in OCCC through the modulation of multiple tumor biological functions." (PMID 39857966, 2025). "The induction of some proteins that were overexpressed in our CT26-bearing spleen model has been previously reported and it led to a poor prognosis in colorectal patients, such as Carbonic anhydrase IX (fold change tumor/control: FC: 26.155), protein S100A4 (FC: 23.44), and galectin-1 (FC: 10.25)." (PMID 38612832, 2024). "S100A4 is a calcium-binding protein, and its role in different biological processes (e.g., angiogenesis, invasion, stemness) has been described in different tumor cell types." (PMID 38339353, 2024). "Beside the common expression of Pan-Ck, tumor cells were characterized by the expression of markers associated with tumor progression, epithelial-to-mesenchymal transition, and resistance to therapy, such as CD44, S100A4 and CA-IX." (PMID 39575252, 2024). "Moreover, increased S100A4 expression significantly correlates with tumor angiogenesis, cell survival, motility, invasion, and metastasis." (PMID 38529274, 2024). "Interestingly, we identified an NFAT binding site next to the NF‐κB binding site in the S100A4 enhancer region, which is a transcription factor activated by phosphatase calcineurin and plays crucial roles in T‐cell function and tumour immune evasion." (PMID 39415352, 2024). "However, in another study, S100A4+ CAFs contributed to tumor suppression by depositing collagen around carcinogens and preventing DNA damage to epithelial cells." (PMID 38443595, 2024). "Additionally, the over-expression of S100A4, observed in over half of the tumor samples, further supports its role in tumor aggressiveness and progression." (PMID 39205741, 2024). "S100A4 monoclonal antibodies could provide additional research directions leading to new drug developments, as they demonstrated efficacy in limiting tumor invasion and metastasis in murine models and cell cultures." (PMID 39830522, 2024). "Patient tumour tissues were analyzed by IHC assays using an S100A4 antibody." (PMID 39415352, 2024). "Thus, Smad4 in S100A4+ macrophages plays a tumor-inhibiting role in CAC development and supports its use as a prognostic marker in CRC patients." (PMID 39664586, 2024). "We found that the tumour parenchyma, especially near keratins, showed positivity of S100A4." (PMID 38906852, 2024). "GB CAFs were defined as non-tumor cells, based on copy number variation (CNV) analyses, expressing typical CAF-associated markers such as α-SMA, COL1A1, FAP, TNC, PDGFR-α, PDGFR-β, PDPN, VIM and S100A4." (PMID 38396962, 2024). "Moreover, although there was a significant fall in percent primary tumour cells stained for S100A4 after injection of RGC (Student’s t-test, p ≤ 0.026), the few tumours that grew as experimental lung metastases showed no significant reduction (p ≥ 0.32)." (PMID 37509135, 2023). "The switch to a predominantly nuclear location for S100A4 in primary tumours in mice treated with RGC may suggest changes in S100A4 modification/transport, but its biological significance here is unknown." (PMID 37509135, 2023). "Of note, HMG family proteins such as HMGB1, HMGB2 and HMGB3 are elevated in human tumor cell NEPs in contrast to S100a4 in mice suggesting that NEP signaling through the RAGE pathway may be conserved between mice and humans." (PMID 36973439, 2023). "Finally, we found that neoadjuvant chemotherapy (NACT)/chemoradiotherapy (NCRT) can reverse the activity of S100A4 from the pro-tumor to favorable one." (PMID 36895491, 2023).